CSPG4 (chondroitin sulfate proteoglycan 4)
Diseases named in the same sentence as CSPG4 in open-access papers (continued):
Sharing a sentence is not in itself a finding about the gene and the disease.
glioma (continued). "In slowly growing gliomas, cells expressed NG2/CSPG4, as well as Olig2, Sox10, and Nkx2.2, all markers of committed progenitor cells to the oligodendroglial lineage, but not O4, a marker of late and adult OPCs." (PMID 30213051, 2018). "Numerous prognostic markers have been proposed for gliomas and among these NG2/CSPG4 - a unique transmembrane chondroitin sulphate proteoglycan (CSPG) – has been suggested to be one of the foremost." (PMID 24386429, 2013). "To test this hypothesis, we treated glioma cells with cytochalasin D, an actin depolymerase (2 μM, 15 minutes) before adding NLGN3 and performing a western blot to detect CSPG4 ectodomains in conditioned medium." (PMID 40791371, 2025). "This analysis identified CSPG4, PTPRZ1, and BCAN as the most highly expressed and concordant ECM targets in adult gliomas, while GPC1, CSPG5, and TNR were the top concordant targets in pediatric gliomas." (PMID 40517137, 2025). "Notably, tumor-initiating cells (TICs) or cancer stem cells (CSCs) are considered to be localized at the perivascular niche in glioma tissues, while CD44 and CSPG4 serve as critical markers of TIC." (PMID 34944101, 2021). "NG2/CSPG4 was detected in the vascular pericytes or ECs of normal blood vessels or quiescent tumor blood vessels neither in low- nor in high-grade gliomas (LGGs and HGGs, respectively)." (PMID 32599896, 2020). "To directly assess this hypothesis, we treated in vitro cell cultures of glioma cells with recombinant NLGN3 ectodomain proteins for one hour, collected the conditioned medium, and performed western blot analysis using antibodies against the CSPG4 N-terminus." (PMID 40791371, 2025). "Notably, this NLGN3-induced proliferation was attenuated by first pre-treating glioma cells with ADAM10 inhibitor, even in the presence of NLGN3, consistent with the hypothesized role for ADAM10-mediated CSPG4 cleavage in the NLGN3-CSPG4-PIEZO1 mechanism." (PMID 40791371, 2025). "Importantly, this increase was dependent on the presence of CSPG4 as we did not observe changes in membrane tension in CSPG4 KO glioma cells." (PMID 40791371, 2025). "Differentially expressed genes (DEGs) in the glioma samples relative to normal samples were screened from the GEO database, and five prognostically relevant BM-related genes, including NELL2, UNC5A, TNC, CSPG4, and SMOC1, were selected using Cox regression analyses for the risk score model." (PMID 36292695, 2022). "Forty years ago, NG2/CSPG4 proteoglycan (PG) was discovered as a marker of oligodendrocyte precursor cells (OPCs), together with platelet-derived growth factor receptor á (PDGFR-á) in the developing central nervous system (CNS) and CNS cancers such as gliomas." (PMID 35891187, 2022). "Interestingly, interaction of CSPG4 with PDGFRA has been shown to promote oligodendrocyte progenitor cells proliferation in response to PDGF43 and a HS modification enzyme, SULF2, is also able to mediate PDGFRA activity in glioma cells." (PMID 32019907, 2020).
triple-negative breast carcinoma (23 papers, 2014 to 2026). An invasive breast carcinoma which is negative for expression of estrogen receptor (ER), progesterone receptor (PR), and human epidermal growth factor receptor 2 (HER2). "In triple-negative breast cancer, CSPG4 has been associated with metastasis formation and crucial functions in the tumor microenvironment." (PMID 31779130, 2019). "Findings to-date indicate a link between the expressions of carbohydrate sulfotransferase-11 (encoded by CHST11) which is involved in decorating CSPG4 with chondroitin sulfate and the metastatic behavior of triple-negative breast cancer cells." (PMID 29375561, 2017). "Our data indicate that VT68.2 binds to CSPG4-positive triple-negative breast cancer cells and that N-glycosidase treatment reduces this binding." (PMID 36768830, 2023). "Given its role in malignancy and its immunogenicity, CSPG4 is a promising target for developing therapeutic approaches for solid tumors, including triple-negative breast cancer." (PMID 36768830, 2023). "Elevated CSPG4 expression is observed in several aggressive tumors, including ovarian cancer, osteosarcoma, and triple-negative breast cancer." (PMID 37854594, 2023). "CSPG4 is also expressed in the triple-negative breast cancer, which is insensitive to available targeted therapies." (PMID 35324891, 2022). "Overexpression of CSPG4 has been found in several cancer types including triple-negative breast cancer, sarcomas, and squamous cell carcinoma of the head and neck." (PMID 35501919, 2022). "Blocking of CSPG4 with the CSPG4-specific antibody on triple-negative breast cancer (TNBC) cells inhibits cell growth, adhesion, and migration." (PMID 32240230, 2020). "Expression of CSPG4 in triple-negative breast cancer (TNBC) in particular is of special value, since this subtype represents an area of unmet need for novel targeted therapies." (PMID 29375561, 2017). "Therefore, the current study was performed to define the glycan specificity of anti-CSPG4 antibodies and to understand the glycan dependency of CSPG4 reactivity with triple-negative breast cancer (TNBC) cells." (PMID 36768830, 2023). "Based on these principles, two preclinical studies were recently described with 212Pb-225.28 for the targeting of chondroitin sulfate proteoglycan 4 (CSPG4) overexpressed in triple-negative breast cancer and 212Pb-376.96 to the protein B7-H3 (CD276) in human pancreatic ductal adenocarcinoma (PDAC)." (PMID 34207408, 2021). "Furthermore, a more recent preclinical study evaluating mAb 225.28 radiolabeled with 212Pb showed efficacy against triple negative breast cancer cells expressing CSPG4, both in vivo and in vitro." (PMID 29375561, 2017). "8/15 and 7/11 tumors in human clusters 1 and 2 respectively expressed CAF markers FAP/CSPG4, which may suggest a propensity for some lung squamous and triple-negative breast cancers (TNBC) to retain patient stroma." (PMID 26980748, 2016). "Additionally, targeting CSPG4 may lead to targeted therapy for triple-negative breast cancer patients who do not benefit from therapies apart from standard chemotherapy." (PMID 29375561, 2017).
sarcoma (20 papers, 2014 to 2026). A usually aggressive malignant neoplasm of the soft tissue or bone. "For example, increased CSPG4 levels has been linked to superior engraftment ability and enhanced local growth of sarcoma cells in culture settings." (PMID 36428658, 2022). "Driving oncogenic mutations in Ng2/Cspg4-expressing cells leads to the formation of sarcomas." (PMID 36221119, 2022). "Because Ng2/Cspg4 is expressed in mesenchymal precursor cells and could play a role in regulating stem cell-like properties, and driving oncogenic mutations in Ng2/Cspg4 expressing cells results in sarcoma formation, we investigated the role of Ng2/Cspg4 in tumor initiation in the mouse." (PMID 29196603, 2018). "In a sarcoma study, CSPG4 deletion at the time of tumour initiation, and before establishment of the tumour, resulted in larger tumours, while suppression in established tumours resulted in reduced tumour growth." (PMID 36428658, 2022). "CSPG4, a cell surface proteoglycan, emerged as a potential therapeutic target for immune therapy in different cancers, including sarcomas." (PMID 35267618, 2022). "Inhibition of Ng2/Cspg4 in established sarcomas by gene deletion or NG2/CSPG4 antibody immunotherapy significantly reduced tumor size in murine and human sarcomas." (PMID 29196603, 2018). "Infection of human primary undifferentiated pleomorphic sarcoma cells with a lentivirus expressing shRNA to NG2/CSPG4 resulted in substantial down-regulation of Ng2/CSPG4 expression, as compared with cells transfected with a control GFP-lentivirus." (PMID 29196603, 2018). "Using the available omics data of 343 cancer cell lines including four sarcoma cell lines, we showed an excellent correlation between the mRNA and protein expression levels of CSPG4, with a Spearman’s rank correlation coefficient (rho) mean equal to 0.85 (p=9E-102)." (PMID 36221119, 2022). "Thus, upon NG2/CSPG4 downregulation in established tumors in murine and human sarcoma models, increased caspase 7 and IGFBP3 genes’ expression reduces tumor size." (PMID 34069554, 2021). "A recent study using murine sarcoma models demonstrated that both malignant bone and soft tissue sarcomas, as well as benign desmoid tumors could originate from CSPG4-expressing pericyte cells." (PMID 29375561, 2017). "Chondroitin sulfate proteoglycan 4 (CSPG4) is a proteoglycan that is expressed at high levels on the cell surface of several tumor types and sarcomas including CS." (PMID 40004005, 2025). "In sarcomas, two studies reported poor-prognostic value in chordoma and soft tissue sarcomas; although, in the latter, NG2/CSPG4 depletion showed divergent effects, depending on the developmental stage of sarcoma." (PMID 35267618, 2022). "Within this range of number of cells injected, knockdown of NG2/CSPG4 did not affect the tumor-initiating potential of the sarcoma cells." (PMID 29196603, 2018). "Whereas this proportion is lower than observed in tumors expressing wildtype Ng2/Cspg4, because these sarcomas lacked Ng2/Cspg4 expression, we know that Ng2/Cspg4 is not required for tumor initiation." (PMID 29196603, 2018). "CSPG4, a cell surface proteoglycan, emerged as a potential therapeutic target for immune therapy in different cancers, including cell therapy based on CSPG4-specific chimeric antigen receptor (CAR)-redirected cytokine-induced killer lymphocytes (CSPG4-CAR.CIKs) in sarcomas." (PMID 35267618, 2022). "Since CSPG4 is expressed in the mesenchymal progenitor cells and pericytes from which STS are supposed to originate, its activation could play a role in sarcoma progression." (PMID 36221119, 2022). "However, the efficacy of targeted NG2/CSPG4 therapy has not been investigated in sarcomas." (PMID 29196603, 2018).
leukemia (17 papers, 2015 to 2025). A malignant (clonal) hematologic disorder, involving hematopoietic stem cells and characterized by the presence of primitive or atypical myeloid or lymphoid cells in the bone marrow and the blood. "Moreover, CSPG4 has been implicated in promoting central nervous system infiltration and leukemia invasiveness." (PMID 31779130, 2019). "Comparably to FRα IgE, CSPG4 IgE bound to human FcεRI-expressing rat basophilic leukemia cells (RBL-SX38) (right)." (PMID 37185332, 2023). "The constructed MLL-r leukemia cell line KOPN8 can activate cocultured CSPG4 CAR T-cells, secreting cytokines and eradicating targeted cells." (PMID 33643279, 2020). "Collectively, uniform CSPG4 expression on KOPN8 leukemia cells suggested possible targetability by CSPG4-CAR T cells." (PMID 31195686, 2019). "In comparison to mock and CEA control CAR T cells, CSPG4-CAR T cells secreted significantly more TNF upon co-culture with KOPN8 leukemia cells." (PMID 31195686, 2019). "On the basis of these data, we encourage a comprehensive screening of MLL leukemia patients for CSPG4 expression to pave the way for further investigations towards a clinical application of CSPG4-CAR T cells against MLL leukemia." (PMID 31195686, 2019). "Here, we provide proof-of-principle data for the use of CSPG4-specific CAR T cells against MLL-translocated leukemias." (PMID 31195686, 2019). "Strikingly, while antigen-specific IL-2 production was detected following co-culture with A375M cells, hardly any IL-2 secretion by CSPG4-CAR T cells was observed upon stimulation with KOPN8 leukemia cells." (PMID 31195686, 2019). "In sum, these data indicated that KOPN8 leukemia cells can be antigen-specifically targeted by CSPG4-CAR T cells." (PMID 31195686, 2019). "The only report on CSPG4-directed targeting of leukemia cell was predicated on the anti-CSPG4 225.28 antibody, the therapeutic efficacy of which against 11q23-rearranged leukemia cells was evaluated in a xenograft mouse model." (PMID 31195686, 2019). "In the present study, we examined the potential of CSPG4 as a novel target antigen for CAR T cell therapy of MLL B-ALL using MLL–MLLT1 rearranged B cell precursor leukemia cells as targets." (PMID 31195686, 2019). "In leukemia, CSPG4 expression is confined to the ill-fated MLL-rearranged subtype, which is characterized by a high intrinsic plasticity facilitating antigen-loss." (PMID 31779130, 2019). "Collectively, the limited expression profile of CSPG4 on leukemia cells indicates that CSPG4-CAR-T cells are primarily conceivable as part of a combinatorial targeting approach to MLL." (PMID 31779130, 2019). "CSPG-4-CAR T cells generated via mRNA electroporation responded to MLL leukemia cells with antigen-specific upregulation of activation markers, antigen-specific elaboration of Th1 cytokines, and antigen-specific tumor cell lysis." (PMID 31195686, 2019). "CSPG4-CAR T cells antigen-specifically lysed KOPN8 leukemia cells even at low effector-to-target ratios." (PMID 31195686, 2019). "Conspicuously, CSPG4 expression is preponderant in the dismally-fated mixed lineage leukemias (MLL), which comprise around 10% of all leukemias and are characterized by specific translocations involving 11q23." (PMID 31779130, 2019). "Next, we examined the cytokine secretion profile of CSPG4-CAR T cells in response to KOPN8 leukemia cells." (PMID 31195686, 2019). "In the following we will discuss the merits and challenges of CSPG4 as a target for the CAR-T-cell therapy of leukemia." (PMID 31779130, 2019). "The observed curative effect seen in animal models of leukemia growth following administration of anti-NG2/CSPG4 antibodies has been attributed to a putative role of proteoglycan in agonizing with bone-marrow resident cells in creating a chemoprotective microenvironment." (PMID 39980017, 2025).
leukemia (continued). "As discussed, the leukemia phenotype may play a role in dictating CSPG4 expression, and the vast number of fusion transcripts associated with KMT2A-r could impact its expression levels." (PMID 35734412, 2022). "In early 2019, we could provide the first proof-of-principle data on CSPG4-CAR-T-cell efficacy against MLL-leukemia using KOPN8 B-cell precursor leukemia cells as a model." (PMID 31779130, 2019). "Having confirmed the presence of our target antigen, we next sought to evaluate whether CSPG4-CAR T cells could antigen-specifically target KOPN8 leukemia cells." (PMID 31195686, 2019). "It has been reported that CSPG4 is expressed on the surface of MLL-rearranged leukemias." (PMID 31195686, 2019). "Finally, CSPG4 is supposed to confer protection against chemotherapy on MLL blasts by preventing leukemia cells to egress from the bone marrow, which constitutes a chemoprotective environment maintained by bone marrow stroma cells." (PMID 31779130, 2019). "Hence, we sought to corroborate the cytotoxic potential of CSPG4-CAR T cells toward KOPN8 leukemia cells by a 4–6 h chromium lysis assay." (PMID 31195686, 2019). "Moreover, CSPG4 expression should be monitored for delayed up-regulation at different time-points during leukemia therapy, especially in the case of phenotypic changes or alterations in leukemia biology, such as increased invasiveness." (PMID 31779130, 2019). "Using the anti-CSPG4 9.2.27 antibody, we could demonstrate uniform CSPG4 surface expression by those leukemia cells." (PMID 31195686, 2019). "Thus, CSPG4-CAR T cells displayed antigen-specific cytotoxicity towards KOPN8 leukemia cells." (PMID 31195686, 2019). "Besides, CSPG4 was not shown to be associated with any pro-oncogenic function in leukemia, which predisposes the generation of CSPG4-negative clones." (PMID 31779130, 2019). "Importantly, we could demonstrate that CSPG4-CAR T cells killed KOPN8 leukemia cells in an antigen-dependent fashion." (PMID 31195686, 2019). "The potential contribution of glycans to the binding of anti-CSPG4 mAbs 225.28 and VT68.2 to leukemia cells was reported." (PMID 36768830, 2023). "Thus, CSPG4 may play an important role in MLL-r leukemia cell adhesion." (PMID 34646384, 2021). "CSPG4-CAR T cells exhibited antigen-dependent upregulation of activation markers and antigen-dependent IFNγ production in response to leukemia cells." (PMID 31195686, 2019). "In sum, CSPG4-CAR T cells revealed a high cytotoxic potential as reflected in antigen-specific degranulation and antigen-specific lysis against KOPN8 leukemia cells." (PMID 31195686, 2019). "While neither mock-transfected nor CEA control CAR-expressing CD8+ T cells displayed any relevant degranulation towards KOPN8 leukemia cells, CD8+ T cells equipped with the CSPG4-CAR exhibited antigen-specific degranulation in response to KOPN8 cells." (PMID 31195686, 2019). "We wish to raise initial awareness for CSPG4 as a possible back-up antigen in B-ALL, with special emphasis on MLL-rearranged leukemias." (PMID 31195686, 2019). "CSPG4-CAR T cells produced significantly more IFNγ than control CEA-CAR T cells and mock T cells upon co-culture with KOPN8 leukemia cells." (PMID 31195686, 2019). "CSPG4-CAR T cells evinced a significantly higher CD69 and CD25 upregulation compared to control CEA-CAR T cells following co-culture with KOPN8 leukemia cells, confirming antigen-specific activation mediated via CSPG4 CAR." (PMID 31195686, 2019). "We transfected bulk T cells with a CSPG4-specific CAR and assayed several canonical T cell effector functions upon co-culture with CSGP4-expressing KOPN8 leukemia cells." (PMID 31195686, 2019). "Considering each subtype of leukemia, the most divergent performance was observed in T-ALL, in which SKIDA1 had the best estimates (AUC: 0.991; CI: 0.981–1.000), followed by LAMP5 (AUC: 0.716; CI: 0.570–0.861), and CSPG4 (AUC: 0.558; CI: 0.418–0.698)." (PMID 35734412, 2022).